ICAM1 (intercellular adhesion molecule 1)
Diseases named in the same sentence as ICAM1 in open-access papers (continued):
Sharing a sentence is not in itself a finding about the gene and the disease.
tumor (continued). "The interaction pairs via SPP1, RARRES2, NECTIN3, LGALS9, and LAMB1 showed increased signaling in the autophagy-high tumor cells, while SEMA3C, PTN, ICAM1, GAS6, and CSF1 showed decreased signaling compared with those in the autophagy-low tumor cells." (PMID 36830707, 2023). "The effect of Nano-reshaper on the structure of tumor blood vessels was determined using CD31, ICAM-1, and VCAM-1 as the markers." (PMID 36702831, 2023). "To assess the impact of IFN-γ production at the tumor site, we analyzed MHC class I, ICAM-1 and PD-L1 expression, which are classically upregulated by IFNs." (PMID 37248395, 2023). "For instance, type I interferons like IFN-β have been shown to increase the tumor cytotoxicity of neutrophils; increase NET, ICAM1 and TNF-α expression; and polarize TANs toward an anti-tumor N1 phenotype in vivo." (PMID 37566060, 2023). "ICAM-1 and VCAM-1 are involved in subsequent adhesion with leukocytes, and they play a role in tumor cells–ECs adhesion." (PMID 37124539, 2023). "Adhesive molecules such as VCAM-1, E-selectin, ICAM-1, and VLA-4 are produced by tumor cells during extravasation to facilitate contact between the tumor and the BBB." (PMID 37818447, 2023). "CX3CL1 upregulates ICAM‐1 expression through the proposed CX3CR1/PLCβ/PKCα/s‐Src/AP‐1 signalling pathway and subsequently promotes tumour metastasis." (PMID 37082943, 2023). "Given that ICAM‐1 expression in cancer cells modulates the activation of CD8+ T cells, tumor tissues' immunological status was analyzed." (PMID 37097643, 2023). "We also verified this phenomenon from co-culture experiments, in which overexpression of ICAM1 on cancer cells enhanced CD69 and PD-1 expression on CD8+ T cells after their direct contact with tumor cells for 24 h." (PMID 36871040, 2023). "Lastly, molecular analyses show that the communication between BC cells and CAFs is dependent on physical interactions, deriving in the production of soluble factors involved in tumour cell survival and proliferation such as RANTES, ICAM1, and CXCL10." (PMID 36949770, 2023). "Our results show that B1R OE stimulated the expression of ICAM-1 and VCAM-1—adhesion molecules—thus promoting the migration and attachment of myeloid cells, particularly monocytes, to tumor cells." (PMID 37627528, 2023). "On blood vessels, RT induces an increase in the production of the integrins ICAM-1 and VCAM-1 in vascular endothelial cells and promotes the transition of CART cells across the vascular endothelium into the tumor tissue." (PMID 37623511, 2023). "CD44, ICAM1, and integrin alpha X (ITAX) are adhesion molecules that participate in cell-cell binding and interaction during inflammation or tumor." (PMID 36860851, 2023). "Therefore, neutralizing IL-17A could recover the interaction of effector CD8+ T cells and tumor vascular endothelium via the LFA-1/ICAM-1, and also restore the NO production from endothelial cells, facilitating the infiltration of CD8+ T cells, particularly the stem-like subset, into the tumor bed." (PMID 37605139, 2023). "Here, we report that ICAM-1 on TNBC cells and CD11b on neutrophils mediate tumor cell–neutrophil binding, providing new insight into the mechanism of CTC–neutrophil cluster formation." (PMID 37345070, 2023). "It is possible that high local concentration at the immunological synapse is needed to prevent ICAM-1/LFA-1 interaction and induce protection from tumor killing." (PMID 37732732, 2023). "ICAM1-DXd can mediate potent and sustained CCA tumor attenuations through comprehensive and synergistic benefits from ADC treatment." (PMID 37717087, 2023). "To evaluate ICAM1 ADCs in a more clinically relevant setting, we further utilized a CCA patient-derived tumor xenograft (PDX) model with the same treatment regimen." (PMID 37717087, 2023).
tumor (continued). "To validate the role of ICAM-1 in controlling tumor cell sensitivity to killing by CTLs, we disrupted ICAM1 in three tumor cell lines expressing low, medium, and high ICAM-1 (HCT 116, Panc-1 and UACC-257, respectively) using two different sgRNAs." (PMID 37732732, 2023). "Records from the TCGA dataset analysis revealed higher levels of ICAM‐1 and VCAM‐1 in tumour specimens compared with the normal specimens." (PMID 37082943, 2023). "In this study, a subset of iCAFs that expresses high levels of the chemokine CCL2, known as ICAM1+ iCAFs, was identified and was found to recruit MDSCs (THBS1+ monocytes) to hypoxic tumor areas by binding to the receptor CCR2." (PMID 37743226, 2023). "The anti-tumor TANs have higher levels of the C–C motif chemokine CCL3, tumor necrosis factor-α (TNF-α), and intercellular adhesion molecule 1 (ICAM1)." (PMID 37496019, 2023). "While we found that adding intercellular adhesion molecule 1 (ICAM-1) targeting can enhance EpCAM CAR T cell activity, resistance and tumor recurrence remained significant challenges." (PMID 38067255, 2023). "To further confirm the role of ICAM-1 and CD11b in mediating tumor cells and neutrophils binding, we sorted ICAM-1+ and ICAM-1− E0771 cells and tested their binding ability with CD11b−/− neutrophils." (PMID 37345070, 2023). "miR-1246 transfection in ECs increased the expression of adhesion molecule ICAM-1 via activation of STAT3, followed by increased tumor cell adhesion to ECs." (PMID 37124539, 2023). "The IFN- signaling pathway stimulates the production of IL12, ICAM1, and tumor necrosis factor (TNF), all of which are deadly to tumor cells and suppress tumor development." (PMID 37728418, 2023). "Tumor cells interact with leukocytes via ICAM-1/LFA-1 (αLß2), which in turn bind to ICAM-1 on the ECs via LFA-1." (PMID 37046617, 2023). "Another potential CSC marker, CD54, also known as intercellular adhesion molecule 1 (ICAM1), was demonstrated to confer self-renewal and tumor malignant transformation capacities to HCC cells." (PMID 36293184, 2022). "An increase in TNFAIP2, ICAM1, and ITGA5 expression pointed to a possible TREM1- and HuR-dependent formation of tertiary structures between tumor and myeloid-derived cells within the inflammatory peri-necrotic areas." (PMID 36249290, 2022). "Tumor cells expression of adherence molecules (CD29 and ICAM1) was also tested on the centralized cohort, along with samples of 31 biopsies from diffuse large B‐cell lymphomas (DLBCL) “not otherwise specified” (NOS) as controls." (PMID 35538643, 2022). "Tumor-derived PCs seem to upregulate PD-L1 expression, a negative regulator of anti-tumor T cell responses, and overexpress the PC marker RGS5, which, together with IL-6, modulates the expression of the adhesion molecule ICAM-1 and promotes T-cell anergy." (PMID 36012149, 2022). "The expressions of serum CXCL13, ICAM-1, MCP-5, IL-7, and TNF-α in tumor-bearing mice treated with rAd-mIL-28B were lower compared to rAd-EGFP-treated mice (P < 0.05)." (PMID 35935577, 2022). "circ0007456 upregulates ICAM-1 by sponging miR-6852-3p in HCC, and overexpression of ICAM-1 has been shown to increase the sensitivity of tumor cells to NK cells." (PMID 36238299, 2022). "Adhesion molecules such as ICAM1 and VCAM-1 on tumor vessels are also upregulated, leading to increased extravasation of T cells to tumor sites." (PMID 36612124, 2022). "CVA21 tumor tropism is driven by the expression of its entry receptor ICAM1, which is highly expressed in NSCLC and other tumor indications." (PMID 36207308, 2022). "In keeping with this, micromolar affinity CARs with specificity for ICAM-1 or CD38 outperformed their nanomolar counterparts in discriminating between normal and transformed cells, while maintaining strong efficacy against tumour cells." (PMID 35883636, 2022). "ICAM-1 and VCAM-1 have been found to be deregulated in tumor EC, possibly due to the high expression of VEGFA." (PMID 35216427, 2022).
tumor (continued). "After exposure to β− particle emission using Sm-153, a bone-seeking radionuclide used to palliate metastatic bone pain, different human tumor cell lines demonstrated upregulation of at least two of the following markers: Fas, MHC-1, ICAM-1, CEA, and MUC-1." (PMID 36497086, 2022). "VEGF promotes, whereas bFGF inhibits, the adhesion of leukocytes via ICAM1 and VCAM1 to the tumour endothelial cells." (PMID 36077754, 2022). "Two studies demonstrated that human umbilical vein endothelial cells cultured with conditioned tumor media underwent epigenetic modifications that resulted in reduced VCAM-1 and ICAM-1 expression." (PMID 36189308, 2022). "At the same time, a set of costimulatory signals are provided, such as B7/CD28, IFA-3/CD2, ICAM-1/IFA-1, which fully activate CTL and produce an anti-tumor immune response." (PMID 35222443, 2022). "The expression levels of other hub genes CTLA4, CXCL10, CCL5, CCl4, ICAM1, CXCL9, CD27, GZMB, FCGR2A, SELL, IDO1 in SKCM were higher than those in non-tumor skin tissues (P < 0.05), and the results were statistically significant." (PMID 35710862, 2022). "Neutrophil-derived vesicles have been shown to target tumor cells and inflammatory endothelium through three pairs of interactions including LFA-1/ICAM-1, β1 integrin/VCAM-1, and CD44/L-selectin." (PMID 35874757, 2022). "Intracellular adhesion molecule 1 (ICAM1) and vascular cell adhesion molecule 1 (VCAM1) are dramatically reduced in tumor vessels determining a critical obstacle for T cells extravasation." (PMID 39086964, 2022). "RT can up-regulate major histocompatibility complex (MHC), apoptosis-related receptors, soluble intercellular adhesion molecule-1 (ICAM-1), TAA and enhance vaccine-mediated tumor cell lysis." (PMID 35198442, 2022). "In vitro tumor cell and TNBC mouse model experiments have revealed that ICAM1-targeted CAR-T cells possess a strong ability to specifically destroy TNBC cells, significantly reduce the growth of TNBC tumors, and improve the survival rate of the mouse model." (PMID 35935930, 2022). "As both control and ICAM-1 KO E0771 cells gave rise to similar tumors at all tested time points, we concluded that ICAM-1 expression by E0771 is dispensable for primary tumor growth in vivo." (PMID 35911772, 2022). "We also showed that probes ICAM1, calreticulin, PD-L1, neuropilin-1, galectin-3 and MPO were spatially associated with immunogenic cell death and, together with the enriched standard cell types, they might serve as an early predictive biomarker of induced anti-tumor immunity in situ." (PMID 35788566, 2022). "NMU overexpression in HT29 cells induced or increased the secretion of tumour supporting cytokines (CXCL1/GROa, CXCL10/IP-10 and ICAM-1/CD54, CCL-5/RANTES, IL-8 and IL-1ra)." (PMID 36482448, 2022). "For this reason, we implanted a very low number of control and ICAM-1 KO E0771 cells embedded in Matrigel in the mammary fat pad of syngeneic C57BL/6 female mice (i.e., 1 × 103 cells) and followed tumor growth 13, 17, and 21 days after implantation." (PMID 35911772, 2022). "To determine the key cytokines secreted by macrophages involved in the induction of ICAM1 in HNSCC, we measured cytokine levels in CM from a tumor–THP-1 coculture system." (PMID 36264639, 2022). "The expression of ICAM-1 and α-SMA in tumor tissue of patients with stage I, II, and III CRC were obtained by using immunofluorescent staining." (PMID 36016615, 2022). "Because many tumors express ICAM1 at high levels, ICAM1 using coxsackieviruses, such as CVA21, preferentially replicate in these tumor cells, thereby inducing tumor cell lysis." (PMID 36298792, 2022). "Some tumors block T cell homing by reducing the expression of adhesion molecules such as ICAM-1, VCAM-1, and CD34 on the tumor endothelium." (PMID 35211124, 2022). "Andrographolide reduces the expression of adhesion molecules such as ICAM-1 by blocking TNF-α-induced Akt phosphorylation in tumor cells, thereby suppressing tumor cell metastasis." (PMID 35682652, 2022).
tumor (continued). "The levels of CXCL13, ICAM-1, MCP-5, and IL-7 in the serum, and the levels of IL-15 and sFasL in the tumor tissue decreased significantly after rAd-mIL-28B treatment relative to rAd-EGFP." (PMID 35935577, 2022). "In this study, we discover that the expression and secretion of ICAM‐1 are induced by radiation and it promotes GBM progression by regulating the tumor microenvironment." (PMID 34813169, 2022). "In support of its tumor-promoting properties, BILF1 has been demonstrated to up-regulate intercellular adhesion molecule-1 (ICAM-1)." (PMID 36497262, 2022). "In line with this, E-selectin, ICAM-1, and VCAM-1 are upregulated on the surface of the activated endothelial cells, which attract the different immune cells to the tumor lesion." (PMID 35327461, 2022). "The JAK/STAT pathway interacts with intercellular cell adhesion molecules (ICAM-1) and VCAM-1 to promote tumor progression." (PMID 36035183, 2022). "Taken together, these data suggest that depleting platelet or inhibiting ICAM‐1 suppresses tumor growth and metastasis after insufficient RFA, and ICAM‐1 activates platelets and leads to increased endothelial permeability after insufficient RFA." (PMID 33643788, 2021). "It is also shown that tumor cells cotreated with TS at 1 μg/ml or TRAIL at 25 ng/ml downregulate the expression of STAT3 target genes (cFLIP, Bcl-xL, ICAM1, VEGF, TRAF1 and the chemokine receptor CXCR4)." (PMID 34543231, 2021). "Microglia and cerebral endothelial cells reacted with an upregulation of ICAM-1 and MHC class I and II antigens, thus meeting the requirements for an anti-tumor T cell immune response." (PMID 34944954, 2021). "In rat models with multiple implanted liver adenocarcinomas, the treatment for one tumor with laser ablation led to an increased expression of CD8, B7-2 (CD86), MHCII, LFA1 (CD11a), and ICAM1 (CD54) at the invasion front of another untreated tumor." (PMID 34830949, 2021). "There are some studies that have shown an interaction between neutrophil Mac-1 (CD11b/CD18; Complement Receptor 3) and ICAM-1 (CD54) on certain tumor cells, which facilitated the metastatic seeding of the tumor cells in the liver and the lungs." (PMID 34572138, 2021). "The ICAM1 knockdown in endothelial cells alone slightly inhibited the TEM of tumor cells, whereas the ICAM1 knockdown in tumor cells resulted in a much more significant reduction in the TEM." (PMID 34381029, 2021). "Immediately after the start of radiation, ICAM-1, the number of adhering WBC on the derma near the tumor, and the number of migrating WBC from the derma near the tumor significantly decreased in both groups." (PMID 34239993, 2021). "Once T cells have infiltrated a tumour, MHC-I, ICAM-1, RAE-1γ and NKG2D promote T cell arrest, tumour cell engagement and were found to be essential for the efficacy of a combination of radiotherapy and CTLA-4 blockade in mice." (PMID 33499003, 2021). "AFP and ICAM-1 have multiple biological functions, for example, recent studies have reported that AFP not only plays a biological role as a tumor marker but also has the ability to regulate cell proliferation, differentiation, and tumorigenesis." (PMID 34696675, 2021). "RT can also induce upregulation of MHC I, the intercellular adhesion molecule-1 (ICAM-1) and membrane protein NKG2D type II on cancer cells, that enhance recognition and cytolysis of tumor by T cells and natural killer (NKs) cells, respectively." (PMID 33530329, 2021). "Combinatorial induction of IL6 and S100A8/A9 in the TME and ICAM-1 and IL8 in the CDX tumor comprise a positive feedback loop that drives inflammation." (PMID 34010296, 2021). "In contrast, antibiotics-induced dysbiosis promoted tumor growth via a suppressed level of TNF-α and a subsequent decrease in tumor endothelial adhesion molecules, especially intercellular adhesion molecule 1 (ICAM-1)." (PMID 34217349, 2021).
tumor (continued). "Using flow cytometry analyses and IHC staining, we first confirmed the highly enriched ICAM1 expression (17–99%) in the lung metastases of three TNBC PDX models (TN1, TN2, and TN3) compared to that of primary tumor cells (0.5–36%, P < 0.05 or 0.01)." (PMID 34381029, 2021). "Angiopoietin-2 can be secreted by tumor ECs, which leads to an autocrine activation of STAT3 signaling with secretion of CCL2 and higher expression of ICAM1." (PMID 34073394, 2021). "Therefore, ICAM‐1 targeted therapy may be used to prevent tumor progression in the future." (PMID 33643788, 2021). "Susceptibility to Vγ9Vδ2 T-cell-mediated killing has also been reported to require tumour cell expression of stress-induced molecules such as NKG2D ligand, ULBP1, ligands for DNAM-1 or the cell adhesion molecule ICAM-1." (PMID 34944832, 2021). "We observed that ICAM1+ tumor cells sorted from TN1 (ICAM1-OE) and TN3 PDXs formed bigger clusters than their counterpart ICAM1− tumor cells over time as measured by IncuCyte imaging." (PMID 34381029, 2021). "A previous study suggests that autophagy facilitates glycolytic metabolism and increases lung colonization by OS cells via upregulating the expression of intercellular adhesion molecule-1 (ICAM-1) and enhancing tumor metastasis." (PMID 34414176, 2021). "The stabilized NOX complexes subsequently result in increased ICAM1 expression and secretion of sICAM1, which contribute to resistance to radiation, transition to CAF and tumor progression in mouse models." (PMID 33466790, 2021). "On the one hand, ICAM-1 can bind more to the ligand LAF-1 and exert its killing effect in tumor cells." (PMID 34386034, 2021). "Combinatorial induction of IL6 and S100A8/A9 in the Hltf-deleted TME with ICAM-1 and IL8 in the primary tumor activated a positive feedback loop." (PMID 34010296, 2021). "Anti-angiogenic therapy: Pro-angiogenic growth factors produced by tumour cells can downregulate the expression of a collection of adhesion molecules (e.g., VCAM-1 and ICAM-1), inhibiting extravasation of T lymphocytes across the tumour endothelium." (PMID 33917287, 2021). "Mesothelial intercellular adhesion molecule 1 (ICAM-1) and tumor cell CD43 (sialophorin) mediate adhesion between mesothelial and tumor cells in ovarian, colorectal and PDA cells." (PMID 32780245, 2020). "Increased ICAM-1 and VCAM-1 expression by the tumor vasculature in response to the pro-inflammatory agent CpG-ODN correlated with improved CD8+ T cell trafficking in a mouse model of pancreatic islet cell carcinoma (RIP1-Tag5)." (PMID 33262763, 2020). "Quantification of the biodistribution [111In]In-anti-ICAM-1 and [111In]In-mIgG2a showed significantly higher uptake in PSN-1 tumour xenografts of the former compared to the latter, at 72 h post administration (19.9 ± 1.2 versus 6.9 ± 0.5%ID/g; P < 0.0001)." (PMID 32135474, 2020). "It is further demonstrated that the developed ICAM1 ADC induces potent and durable tumor regression in an orthotopic PC mouse model." (PMID 33344137, 2020). "Treatment with 3 μM CBD induced ICAM-1 expression and LAK cell-mediated tumor cell lysis in A549 and H460, along with metastatic cells from a patient with NSCLC." (PMID 33143283, 2020). "ICAM‐1 expressed on LSECs promoted secretion of IL‐6, prostaglandin E2, VEGF, and MMP2 by tumor cells, which in turn induced VEGFA and MMP2 secretion by HSCs." (PMID 33252863, 2020). "The mechanisms by which tumor vessel normalization enhances TIL infiltration are likely to be mediated through chemokines and adhesion molecules, such as CXCL9/10 and ICAM1/E-selectin, respectively." (PMID 32759497, 2020). "The higher lytic activity of CIK cells is mainly due to the higher proliferation of CD3+CD56+ cells and cytotoxic effects of CIK cells against tumor cells is blocked by antibodies of LFA-1 and its counter receptor (ICAM-1)." (PMID 32349280, 2020).